MBP (myelin basic protein)
Diseases named in the same sentence as MBP in open-access papers (continued):
Sharing a sentence is not in itself a finding about the gene and the disease.
renal disease (1 paper, 2014). "The mean age, BMI, MBP, serum lipids, distribution of primary renal disease, CVD history, prevalence of DM were not significantly different between those who had measured UA and those who did not (2193 patients) (P>0.05)." (PMID 24416142, 2014).
retinopathy (1 paper, 2019). "MBP immunization led to very mild disease without significant retinopathy." (PMID 31684959, 2019).
MBP also shares sentences with these, for which no sentence is quoted: mental disorder (4 papers); multiple system atrophy (4); celiac disease (3); allergies (2); colorectal cancer (2); Crohn disease (2); meningitis (2); myasthenia gravis (2); Myelopathy (2); open-angle glaucoma (2); Parkinsonism (2); Pleural effusion (2); progressive multifocal leukoencephalopathy (2); type 1 diabetes (2); vascular dementia (2); acute liver failure (1); acute transverse myelitis (1); adenocarcinoma (1); age-related macular degeneration (1); AIDS dementia complex (1); alcohol use disorders (1); anaplastic oligodendroglioma (1); Ascites (1); aspergillosis (1); asphyxia (1); atopic dermatitis (1); attention deficit-hyperactivity disorder (1); B cell lymphoma (1); bacterial infections (1); bleeding (1).
A further 73 diseases each share a sentence with MBP in 1 paper.